SNORA27 (small nucleolar RNA, H/ACA box 27)
Synonyms: ACA27
Gene: Small nucleolar RNA gene on chromosome 13 (27,255,401 to 27,255,526, forward strand). Ensembl gene ENSG00000207051.
Gene Ontology:
Biological process: RNA processing
Cellular component: nucleolus
Homologues: Orthologues: chimpanzee SNORA27 (100% identical), macaque SNORA27 (98% identical), rabbit SNORA27 (91% identical), mouse Gm23202 (89% identical), rat Snora27 (88% identical).